C9orf78 (chromosome 9 open reading frame 78)
Description:
Plays a role in pre-mRNA splicing by promoting usage of the upstream 3'-splice site at alternative NAGNAG splice sites; these are sites featuring alternative acceptor motifs separated by only a few nucleotides. May also modulate exon inclusion events. Plays a role in spliceosomal remodeling by displacing WBP4 from SNRNP200 and may act to inhibit SNRNP200 helicase activity. Binds U5 snRNA. Required for proper chromosome segregation. Not required for splicing of shelterin components.
Synonyms: HCA59; HSPC220; CSU2; TLS1; bA409K20.3
Tractability: Small molecule: a structure with a bound ligand is known. PROTAC: ubiquitination databases record sites on it; its protein half-life has been measured.
Gene: Protein-coding gene on chromosome 9 (129,827,194 to 129,835,863, reverse strand). Ensembl gene ENSG00000136819.
Subcellular location: Nucleus; Chromosome, centromere
Subcellular location (Human Protein Atlas): Nucleoplasm
Pathways (Reactome):
Metabolism of RNA: mRNA Splicing - Major Pathway
Gene Ontology:
Molecular function: protein binding; U5 snRNA binding
Biological process: mRNA cis splicing, via spliceosome; regulation of homologous chromosome segregation; mRNA splicing, via spliceosome
Cellular component: chromosome, centromeric region; nucleoplasm; nucleus; spliceosomal complex
Genetic constraint (gnomAD): Loss-of-function variants: 9 observed, 20.55 expected, observed/expected ratio (o/e) 0.44, 90% interval 0.26 to 0.76. The upper end of that interval is the gene's LOEUF score, 0.76, which puts it in group 3 of 6, group 1 being the genes least tolerant of losing a copy. Missense variants: 165 observed, 227.52 expected, observed/expected ratio (o/e) 0.73, 90% interval 0.64 to 0.82. Synonymous variants: 80 observed, 81.54 expected, observed/expected ratio (o/e) 0.98, 90% interval 0.82 to 1.18.
Homologues: Orthologues: chimpanzee C9H9orf78 (100% identical), pig C9orf78 (98% identical), dog C9H9orf78 (98% identical), mouse BC005624 (96% identical), guinea pig C9orf78 (96% identical), rat C3h9orf78 (87% identical), tropical clawed frog c8h9orf78 (81% identical), zebrafish C5H9orf78 (78% identical), rabbit C9orf78 (52% identical), Drosophila melanogaster CG7974 (49% identical), Caenorhabditis elegans T23G11.4 (26% identical).
Diseases named in the same sentence as C9orf78 in open-access papers:
C9orf78 is named in the same sentence as 5 diseases in open-access papers, as found by Europe PMC text mining. Sharing a sentence is not in itself a finding about the gene and the disease. The quoted sentences say what the papers report.
hepatocellular carcinoma (2 papers, 2014 to 2024). A malignant tumor that arises from hepatocytes. "Likewise, C9orf78 was overexpressed in hepatocellular carcinoma and several other cancer cell lines but not in their normal tissue counterparts, indicating a possible role of this protein in tumorigenesis." (PMID 38215077, 2024). "Its human homologue, C9ORF78, was originally identified as a factor that is overexpressed in hepatocellular carcinoma and a number of other cancer cell lines, but not in their normal tissue counterparts, indicating a possible role of this protein in tumorigenesis." (PMID 25245948, 2014).
cancer (4 papers, 2014 to 2024). A tumor composed of atypical neoplastic, often pleomorphic cells that invade other tissues. "Its mammalian homologue is the uncharacterized gene C9ORF78, which is overexpressed in a number of cancer cell lines." (PMID 25245948, 2014). "Given that its human homologue C9ORF78 also associates with the spliceosome and is overexpressed in multiple cancer cell lines, our results suggest that C9ORF78 overexpression might alter the proper splicing of genes during cancer progression." (PMID 25245948, 2014). "Given the prevalence of splicing misregulation in cancer cells, it is interesting to examine whether C9ORF78 also regulates the proper splicing of mRNAs and whether such misregulation underlies tumorigenesis." (PMID 25245948, 2014). "Our results suggest that overexpression of C9ORF78 might affect proper mRNA splicing to affect cancer progression." (PMID 25245948, 2014).
tumor (2 papers, 2023 to 2024). "In particular, the STK3, C9orf78 and STRN3 genes were the direct targets of both miR-34c and miR-449a, and their regulation are predictive of tumour progression." (PMID 38215077, 2024).
C9orf78 also shares sentences with these, for which no sentence is quoted: infection (1 paper); lung carcinoma (1).